CCN1 (cellular communication network factor 1)
Diseases named in the same sentence as CCN1 in open-access papers (continued):
Sharing a sentence is not in itself a finding about the gene and the disease.
infection (20 papers, 2015 to 2024). The state of being infected such as from the introduction of a foreign agent such as serum, vaccine, antigenic substance or organism. "Mice with myeloid-specific Ccn1 deletion and knock-in mice expressing CCN1 unable to bind αvβ3 are more susceptible to infection by S. aureus or P. aeruginosa, resulting in increased mortality and organ colonization." (PMID 32144270, 2020). "The ability of CCN1 to enhance bacterial clearance may contribute to the healing of wounds at risk of infections." (PMID 32144270, 2020). "The YAP1/TAZ targets, CTGF/CCN2, and CYR61/CCN1 also showed upregulation, suggesting successful infection of human acinar cells with YAP15SA and TAZ4SA." (PMID 38247878, 2024). "CCN1 expression increased after the infection of astrocytes with certain viruses, such as Zika virus and coxsackievirus B3." (PMID 38666951, 2024). "Consistent with findings from other researchers, our study revealed an elevation in CCN1 expression in placental villous tissue after the infection of SARS-CoV-2." (PMID 38666951, 2024). "At 48 h post-infection, cells were harvested to assess the level of CCN1, phospho-CREB, phospho-c-Jun, and phospho-c-Fos using Western blotting." (PMID 35418961, 2022). "The results showed that CCN1 mRNA was elevated gradually at 36 and 48 h after infection; CCN1 protein expression was also increased significantly at 36 and 48 h after PEDV infection." (PMID 35418961, 2022). "Ccn1 is essential for efficient bacterial clearance in mouse models of infection, and administration of CCN1 protein markedly accelerates bacterial clearance." (PMID 32144270, 2020). "We observed an increase in phosphorylation of p38 as well as the ER stress marker GRP-94 following Ad.mda-7 or Ad.CCN1-CTV-m7 infection and a decrease in expression of the anti-apoptotic Mcl-1 protein." (PMID 25926554, 2015). "Infection with Ad:ActinR62D resulted in a significant inhibition (to 35.3 ± 14%; p < 0.05) of CCN1 mRNA levels, compared to Ad:Control infected cells, consistent with monomeric actin mediated repression of CCN1 expression." (PMID 25446180, 2015). "Firstly, CCN1 exhibits the capacity to incite sterile inflammation, even in the absence of infection, therefore causing endothelial cell injury." (PMID 38755602, 2024). "At 48 h post-infection, CCN1 expression was analyzed by RT-PCR." (PMID 35418961, 2022). "However, as for other pathogen infections, it was found that S. aureus and its supernatants could induce the expression of CCN1 in epithelial cells, while the expression of CCN1 was inhibited by Salmonella enterica." (PMID 35269881, 2022). "Further studies can be focused on CCN1-deficient mice to confirm the role of CCN1 and the specific mode of interaction between CCN1 and TLR2/4 signaling pathways after infection, which may prompt novel therapies for pathogen infections." (PMID 35269881, 2022). "At 0 h post-infection (control group), the upregulated proteins were enriched in function of cell development (through proteins such as HAND1 and CCN1); a pattern that was lost in the SARS-CoV-2 infected hiPSC-derived cardiomyocytes." (PMID 38087340, 2023). "Furthermore, L. monocytogenes infection caused the increased expression of CCN1 and the activation of TLR2/4 signaling pathways, and the interaction between these occurred after infection, which may be the reason for the increase in pro-inflammatory cytokines secretion." (PMID 35269881, 2022). "Subsequently, 24 h post-infection, an increase in ZIKV-E protein expression was detected in the CCN1 group compared with that in the control and NS-CCN1 groups." (PMID 31957543, 2020). "Toanalyse the effect of CCN1 on viral replication and release, intracellular and extracellular ZIKV RNA were measured by RT-qPCR analysis 60 h post-infection." (PMID 31957543, 2020). "SGC-CBP30 reduced the expression of CCN1 and ZIKV-E protein 24 h post-infection." (PMID 31957543, 2020).
infection (continued). "To investigate whether viral invasion or viral replication could induce increased CCN1 expression, we used UV inactivated ZIKV UV-ZIKV in infection assays." (PMID 31957543, 2020). "To determine how CCN1 may contribute to the inflammatory response, we tested whether CCN1 can by itself induce inflammation without infection." (PMID 32144270, 2020). "infection), indicating that CCN1 also defends against infection by Gram-negative bacteria." (PMID 32144270, 2020). "Infection with Ad:RhoAG14V did not significantly alter basal CCN1 mRNA levels." (PMID 25446180, 2015). "However, it is not clear whether the infection of PEDV can regulate the expression of CCN1 and whether CCN1 affects the replication of PEDV." (PMID 35418961, 2022). "Thus, although CCN1 expression is low in neurons without SARS-CoV-2 infection, upregulation of CCN1 may occur after the infection." (PMID 32934757, 2020).
retinopathy (7 papers, 2014 to 2024). "The degree of retinopathy was evaluated by staining retinal sections with hematoxylin and eosin, and the expression of CCN1, HIF-1α, VEGF, caspase-3, Bcl-2, IL-1β, and TNF-α protein was analyzed by Western blotting and immunohistochemistry." (PMID 35445044, 2022).
bacterial infection (5 papers, 2014 to 2024). "Here, the authors identify a possible mechanism by showing that CCN1 mediates the clearance of bacterial infections in mice and activates TLR signalling." (PMID 32144270, 2020). "Given that CCN1 opsonizes bacteria for phagocytosis and killing, we investigated the role of CCN1 in host defense against bacterial infections in animal models." (PMID 32144270, 2020). "CCN1, recognized as a pro-inflammatory cytokine involved in regulating inflammatory molecules, is known to exhibit upregulated expression in response to viral or bacterial infections." (PMID 38666951, 2024). "Given the strong protective role of CCN1 against bacterial infections, we tested whether administration of exogenous CCN1 protein may accelerate bacterial clearance in infected mice." (PMID 32144270, 2020). "Future investigation into the potential efficacy of CCN1 and CCN1-derived peptides may prompt novel therapies for bacterial infections recalcitrant to conventional treatments." (PMID 32144270, 2020). "To our surprise, we found that CCN1 can by itself induce inflammatory responses in the absence of bacterial infection through physical interaction with TLR2 and TLR4 to activate MyD88-dependent signaling." (PMID 32144270, 2020). "Altogether, these results show that CCN1 can directly bind and activate TLR2 and TLR4 and may function as a DAMP to regulate inflammatory responses, independent of bacterial infections." (PMID 32144270, 2020).
inflammation (5 papers, 2018 to 2020). Aberrant reaction of the microcirculation characterized by movement of fluid and leukocytes from the blood into extravascular tissues. "Combined with the previous studies that CCN1 secretion induced by cigarette smoking extracts augments IL-8 release from bronchial epithelial cells, our current report further extended the importance of CCN1 in triggering lung inflammation." (PMID 28638955, 2018).
kidney disease (3 papers, 2013 to 2025). "This study aimed to validate and characterize the angiogenic potential and mechanisms of MD-derived biologicals including CCN1 in control healthy and kidney disease conditions." (PMID 40843448, 2025). "The present study confirmed the strong angiogenic effect of MD-derived factors including CCN1 that may be targeted in future biologicals, biofabricated tissue, or cell-based therapeutic developments for kidney diseases." (PMID 40843448, 2025).
cardiovascular disease (2 papers, 2021 to 2022). "CCN1 plays a crucial role in the modulation of cardiovascular diseases." (PMID 33906697, 2021).
CCN1 also shares sentences with these, for which no sentence is quoted: endometrial cancer (11 papers); cervical cancer (9); esophageal squamous cell carcinoma (7); non-small cell lung carcinoma (7); adenocarcinoma (6); chronic obstructive pulmonary disease (6); lymph node metastasis (5); neuroblastoma (5); acute coronary syndrome (4); acute myeloid leukemia (4); Cirrhosis (4); invasive breast carcinoma (4); pancreatic adenocarcinoma (4); preeclampsia (4); pulmonary hypertension (4); squamous cell carcinoma (4); basal cell carcinoma (3); coronary artery disease (3); heart failure (3); hypospadias (3); lung adenocarcinoma (3); mesothelioma (3); metastatic disease (3); Miscarriage (3); multiple myeloma (3); Sjogren syndrome (3); acute lymphoblastic leukemia (2); adrenocortical cancer (2); apical periodontitis (2); atrial septal defect (2).
A further 139 diseases each share a sentence with CCN1 in 2 papers or fewer.